CDK4 (cyclin dependent kinase 4)
Diseases named in the same sentence as CDK4 in open-access papers (continued):
Sharing a sentence is not in itself a finding about the gene and the disease.
cancer (continued). "As a result, CDK4/6 inhibition promotes cell senescence and apoptosis, offering a therapeutic strategy for certain cancers." (PMID 39270064, 2024). "NT431, a newly synthesized 4-fluorobenzyl-abemaciclib, exhibited high potency to CDK4/6 and against four cancer cell lines with IC50 similar to that of the parent abemaciclib." (PMID 38999983, 2024). "These encouraging in vitro results with NT431 demonstrated high CDK4/6 inhibition in kinase activity assay combined with high efficacy against various cancer cell lines warranting the radiosynthesis of [18F]NT431 and the subsequent in vivo evaluation." (PMID 38999983, 2024). "Second, in cancers where combined CDK4/6 and CDK2 inhibition is warranted, separation of these components allows for flexibility with dosing, increasing the chances of finding an effective and tolerable treatment schedule." (PMID 38047585, 2024). "Of note, clinical trials using a combination of CDK4/6is with immunotherapy have demonstrated promising potential for cancer patients." (PMID 39593745, 2024). "Targeting the CDK-RB-E2F axis for cancer therapy is becoming an increasingly attractive strategy due to recent advances in developing specific small molecule inhibitors targeting either CDK4/6 or E2Fs114,115." (PMID 38678032, 2024). "The inhibition of CDK4/6 prevents cell division and proliferation, ultimately restraining the growth of cancer cells." (PMID 38998978, 2024). "Fascaplysin exhibits anti-cancer effects in various types of cancer cells by inhibiting CDK4 (cyclin-dependent kinase 4)-mediated cell cycle progression." (PMID 38474445, 2024). "In different cancer models, specific inhibition of CDK4/6 not only induces the cell cycle arrest but also a senescent‐like state including a senescence‐associated secretory phenotype (SASP)." (PMID 36453028, 2024). "Preclinical studies using CRISPR-Cas9 have shown promising results in inhibiting CDK4 expression and reducing tumor growth in various cancer models, such as melanoma, breast cancer, and glioblastoma." (PMID 38195537, 2024). "The primary anti‐cancer mechanism of CDK4/6i is suppression of RB phosphorylation, enforcing G1 cell cycle arrest, thus inhibiting cancer cell proliferation." (PMID 39009505, 2024). "The clinical exploration of CDK-4/6 inhibitors has led to the improved outcomes of some cancer treatments and an increased focus on the exploration of other CDKs." (PMID 38184514, 2024). "Cyclin dependent kinase 4/6 inhibitors (CDK4/6i) are a recently approved class of drugs (February 2015) that target enzymes important in cell division and thus can interrupt the growth of cancer cells." (PMID 38922546, 2024). "As expected, the levels of γH2AX and cytoplasmic dsDNA were found increased in Cdk4−/− and Cdk6−/− cancer cells." (PMID 37833461, 2023). "Both OXPHOS and cancer stem cells have been reported to be essential factors for the failure and recurrence of CDK4/6i therapy." (PMID 37452037, 2023). "Among these patients, more than 35% experienced disease progression and cancer recurrence during CDK4/6 inhibitor treatment for 2 years." (PMID 36127291, 2023). "Chemotherapy and radiotherapy are the major treatment methods for patients with cancer, although many others, such as immunotherapy, epigenetic modulators, and CDK4/6 inhibitors, are also in use." (PMID 37771436, 2023). "Compared with CDK4/6 degraders and inhibitors, this novel platform showed remarkable efficiency in suppressing cancer cell proliferation." (PMID 36982263, 2023). "Our studies offer insights into the conformational changes involved in cyclin-E/CDK2 and cyclin-D/CDK4 activation and their implications for drug discovery, particularly for CDK4, which is often targeted in cancer." (PMID 37790340, 2023). "CDK overexpression is associated with cancer, and breast and skin cancer treatment with curcumin decreases cancer progression by inhibiting CDK4." (PMID 37049544, 2023).
cancer (continued). "CDK4/6 are important regulators of cell cycle and their inhibitors have been approved as anti-cancer drugs." (PMID 37833461, 2023). "The main difference between radiotherapy and CDK4/6 inhibitors is their cancer control: radiotherapy drives cells to certain cell death, while CDK4/6 inhibitors block the cell cycle at the G1/S checkpoint." (PMID 37886029, 2023). "In cancer cells, for G1 to S-phase transition in the cell cycle, CDK-4 or CDK-6 make a complex with cyclin D, and CDK-2 makes a complex with cyclin-E." (PMID 36597025, 2023). "CDK4 is a key mediator of the cellular transition to the S phase and is important for the initiation, growth, and survival of several cancer types, including B-ALL." (PMID 37542030, 2023). "More studies on the effect of CDK4/6 inhibition on other cell types are clearly needed to understand better the effect of CDK4/6i in the interaction between host and cancer cells." (PMID 37835528, 2023). "The role of p57(Kip2) as a gatekeeper preventing commitment past the G1/S transition makes it a very attractive option, especially with the recent focus on CDK4/6 inhibitors like the FDA approved cancer drug palbociclib." (PMID 37035141, 2023). "The CDK4 gene is frequently amplified in human cancer, and its deregulation has been frequently observed." (PMID 37373242, 2023). "Cyclin D1, along with its main partner cyclin-dependent kinase 4 (Cdk4), is a pivotal cell cycle regulator and driver oncogene that is overexpressed in many cancers." (PMID 38152849, 2023). "CDK4 is a well-known cancer treatment target, and CDK4 inhibitors (e.g., abemaciclib and palbociclib) have demonstrated cytostatic activity in HPV-negative HNSCC, whereas their effects on HPV-positive HNSCC are not obvious." (PMID 36811599, 2023). "CDKN2B, also known as P15, belongs to the INK4 family, which has been identified as an inhibitor of cyclin-dependent kinase 4, thus inhibiting cell cycle progression and facilitating cell apoptosis in a variety of human cancers." (PMID 36776317, 2023). "The CDK 4 and 6 (CDK4/6) retinoblastoma (Rb) pathway is dysregulated in approximately 80% of human cancers." (PMID 37369022, 2023). "Although neuropilins primarily function as vascular endothelial growth factor (VEGF) coreceptors in cancer, their interactions with CDK4, EGFR, RAS, BRAF, PI3K, and PTEN are not fully understood." (PMID 37885828, 2023). "Most studies with CDK4/6i mainly focused on their effect on cancer cells and, more recently, on immune cells." (PMID 37835528, 2023). "Kinase inhibitors against Cyclin Dependent Kinase 4 and 6 (CDK4/6i) are promising cancer therapeutic drugs." (PMID 37452037, 2023). "Our findings not only address a long-standing question in cell cycle biology but also the design of more targeted and effective inhibitors against CDK4, opening new venues in cancer treatment." (PMID 37790340, 2023). "The CDK4/6 inhibitor, palbociclib, was reported to induce PD-L1 expression in cancer cells, including TNBC." (PMID 37230983, 2023). "Despite cancer cell cycle arrest being the most obvious cellular response to CDK4/6i, the effects of CDK4/6i seem to be more complex than initially thought." (PMID 37835528, 2023). "The G1/S checkpoint, which is the primary regulator of the cell cycle and essential for the onset and advancement of malignant tumors, is regulated by CDK4/6." (PMID 37240281, 2023). "In these tumors, estrogen receptor activity leads to cancer cell proliferation through cyclin-dependent kinase 4 and 6 (CDK4/6) activation and cell cycle progression." (PMID 37386030, 2023). "Here, we performed a comprehensive analysis, including drug screening, pan-cancer genomic dependency analysis, and epigenetic sequencing to identify the candidate combination with CDK4/6 inhibitors." (PMID 36755269, 2023). "Immunohistochemistry showed that the expressions of CDK4/6 and c-Myc in cancer tissues were higher than those in adjacent tissues(P<0.0001)." (PMID 36872049, 2023).
cancer (continued). "PFS on first line CDK4/6 inhibitor ranges from 2–3 years; however, the median OS of about five years suggests limited efficacy of subsequent anti-cancer treatments." (PMID 37046675, 2023). "Depending on the mechanisms of drug-resistance in cancer cells, the protection of normal cells can be achieved with inhibitors of CDK4/6, caspases, Mdm2, mTOR, and mitogenic kinases." (PMID 36913303, 2023). "The isolated PRGPRP peptide from the NK region of the cdk4 protein has been synthesised and placed in cyclic amphiphilic cassettes to allow internal access to cancer cells in tissue culture." (PMID 37279947, 2023). "The combination of CDK2 inhibitors and CDK4/6-inhibitors appears to be effective against cancer cells resistant to CDK4/6 inhibitors." (PMID 37563111, 2023). "Pharmacological blockage of CDK4/6 has been recently investigated in clinic and demonstrated promising activity in patients with breast and other cancers." (PMID 36900358, 2023). "In particular, the overexpression of cyclin D1 (the binding partner of CDK4/6) and the loss of function of p16INK4a (endogenous CDK4/6 inhibitor) lead to abnormal function of CDK4/6, thus compromising the G1/S cell cycle checkpoint in cancer." (PMID 37631380, 2023). "Our multi-dimensional analysis of CDK4/6i plus ET resistance mechanisms revealed a complex interplay between two major cancer hallmarks: unchecked cell proliferation versus genomic instability and DNA damage." (PMID 37475004, 2023). "Cyclin D1 together with cyclin-dependent kinase (CDK)-4 are key regulators of the G1 phase of the cell cycle, and they are considered therapeutic targets in BRAF-mutated cancers." (PMID 36674794, 2023). "The highly connected hub gene CCND1 encodes cyclin D1, which together with CDK4 and CDK6 kinases control G1 to S phase cell cycle progression and is frequently overexpressed in human cancers, promoting tumorigenesis." (PMID 37935712, 2023). "The aberrant overexpression of CDK6 protein is the most recognized reason for CDK4/6i primary and acquired resistance for many cancers, including lung cancer." (PMID 37452037, 2023). "Thus, the HDAC5 deficiency in cancer cells could be useful to drive the clinical use of CDK4/6is." (PMID 37833875, 2023). "Many human cancers have genomic or transcriptional abnormalities that activate CDK4/6, and inhibition of CDK4/6 has become a potential target for the development of antitumor drugs." (PMID 36890610, 2023). "CDK4/6 inhibitors have become the first highly specific CDK inhibitors approved for cancer treatment." (PMID 37529698, 2023). "CDK4/6 is a key molecule involved in the development of various malignant tumors, and compared with pancycle inhibitor drugs, CDK4/6 inhibitors have stronger anticancer effects and less toxicity." (PMID 37225761, 2023). "CDK4 is an important therapeutic target for cancer treatment, such that its inhibitors, including palbociclib, ponatinib and ribociclib, can block cell cycle progression, DNA damage response and immune modulation to suppress the cancer progression." (PMID 37870748, 2023). "This process is intricately regulated by external signals and mitogenic signaling, with aberrations in the CDK4/6-RB-E2F axis observed in various cancers." (PMID 38138549, 2023). "Based on this, an intact RB and high RB expression appeared as one of the first candidate biomarkers to predict CDK4/6i responsiveness in preclinical cancer models." (PMID 36765923, 2023). "The mechanism of CDK4/6 inhibitors targeting cancer is to prevent the transition from G1‐phase to S‐phase of the cell cycle." (PMID 38009308, 2023). "CDK4/6 inhibitors targeted the cell cycle, preventing cancer cells from progressing through the cell division process." (PMID 37653504, 2023). "Cyclin-dependent kinase 4 (CDK4) inhibitors are introduced as novel drugs by targeting and disrupting the CDK4-related cell cycle progression of cancer cells in recent years." (PMID 36811599, 2023).
cancer (continued). "Although we have found that deletion of Cdk4 in cancer cells increased immune cells infiltration and CD8+ T cells activation in TME, its cellular mechanisms remained unclear." (PMID 37833461, 2023). "Herein, we discuss the biological significance of CDK4/6 inhibitors in cancer therapeutics, as well as their biological impact on T cells and other important immune cells." (PMID 36768557, 2023). "Cyclin-dependent kinase 2 (CDK2) has been garnering considerable interest as a target to develop new cancer treatments and to ameliorate resistance to CDK4/6 inhibitors." (PMID 37049714, 2023). "Cyclin-dependent kinases (CDKs) such as CDK4/CDK6 overexpression are common in different cancers including TNBC." (PMID 37190133, 2023). "Functionally, IGF2BP3 can bind to and maintain the stability of downstream mRNAs to promote cancer progression, such as CDK4 and CDK6." (PMID 37407973, 2023). "The mechanism of CDK4/6 inhibitors against cancer is to prevent the transition of cell cycle from G1 phase to S phase." (PMID 38009308, 2023). "Given the effects on cell cycle arrest, there is potential for CDK4/6 inhibitors and radiotherapy (RT) to work synergistically, enhancing the effect of RT due to cancer cells’ arrest in a more radiosensitive phase." (PMID 37366898, 2023). "As an anticancer agent, fascaplysin holds a great potential due to the multiple targets affected by this alkaloid in cancer cells, including inhibition of cyclin-dependent kinase 4 (CDK4) and induction of intrinsic apoptosis." (PMID 37623705, 2023). "CDK4 is widely known to be a cancer promoter gene and it is overactive in the majority of human cancers." (PMID 36769158, 2023). "The application of CDK4/6 inhibitors in cancer treatment is discussed, with a particular focus on their potential in treating kidney diseases." (PMID 37686364, 2023). "A recent study reported the efficacy of CDK4/6–SHP2 co-inhibition in KRAS-mut cancers, which is consistent with our KRAS-amp GEA results." (PMID 36752207, 2023). "Currently, CDK4-targeted drug inhibitors are an emerging approach to cancer treatment, with several drugs already approved by the Food and Drug Administration (FDA) and showing good efficacy in clinical practice." (PMID 38019470, 2023). "CDK4 is overactive in cancer cells, and has a role in cell cycle (dys)regulation, making it an attractive drug target." (PMID 37790340, 2023). "Flow cytometry and immunofluorescence staining showed that tumors developed from Cdk4−/− cancer cells had increased DCs and CD8+ T cells infiltration." (PMID 37833461, 2023). "Some have reported that CDK4/6 inhibitors strengthen cancer cell immunogenicity, promote an immunomodulatory senescence-associated secretory phenotype (SASP), and induce T effector cell infiltration and activation." (PMID 36871040, 2023). "The BCSC secretome rendered the bulk cancer cell population resistant to anti-estrogen and CDK4/6 inhibitor therapy; as well as increased the metastatic burden attributable to bulk cancer cells." (PMID 36915147, 2023). "CDK4 regulates the G0-G1/S checkpoint of the cell cycle, and disruption of its function can lead to cancer." (PMID 37623705, 2023). "In particular, the dysregulation of ubiquitination-dependent degradation of cyclin D1 contributes to not only the pathogenesis of malignancies but also the refractory to cancer treatment regiments with CDK4/6 inhibitors." (PMID 37414783, 2023). "PAQR4 inhibits SKP2-mediated ubiquitination of CDK4 by competitive binding to the binding site, contributing to cancer cell proliferation and carcinogenesis." (PMID 36609413, 2023). "IMMT levels positively correlated with biomarkers linked to cancer proliferation (KI67, PCNA, and MCM2) and with key regulators of the cell cycle (CDK4, CDK2 and CDK1)." (PMID 36899366, 2023).
cancer (continued). "Studies have shown that cyclin D1 is highly expressed in the mid-to-late G1 phase and exhibits an up-regulated kinase activity when bound to cdk4 in cancer cells." (PMID 37370134, 2023). "Two key players of the cell cycle, CDK6 and CCND1, were connected to palbociclib, the first CDK4/6 inhibitor approved for cancer therapy." (PMID 37359725, 2023). "Multiple preclinical studies reported that CDK4/6i can induce a senescence-like state in cancer cells characterized by cellular enlargement and increased senescence-associated β-galactosidase (SAβGal) activity." (PMID 37835528, 2023). "CDK4 regulates cancer cell stemness and has been shown to promote normal stem cell expansion; thus, we examined its participation in the acquisition of stem cell-like properties." (PMID 37373242, 2023). "The third generation of selective CDK4/6 inhibition has proceeded into clinical trials for a range of cancers and is quickly becoming the backbone of contemporary cancer therapy." (PMID 37240281, 2023). "More recently, a systematic evaluation of CDK4/6 as targets in a series 16 pediatric cancer types indicated that further preclinical evaluations are still needed to affirm the dependence of tumors on CDK4/6." (PMID 36839989, 2023). "Molecularly, WD LPS and DD LPS share amplified segments of chromosome region 12q13-15, which contains a number of cancer-related genes implicated in tumorigenesis, including MDM2 and CDK4." (PMID 37760460, 2023). "The cell cycle analysis and down-regulation of Cyclin D1 (CCND1) and cyclin dependent kinase 4 (CDK4) revealed that cancer cells were arrested in the sub-G1 phase." (PMID 36828883, 2023). "The majority of patients were prescribed CDK4 and 6 inhibitors at a designated cancer hospital (85.6%) within a surgery-related department (94.4%)." (PMID 36414795, 2023). "Consistent with previous reports in other cancer types, treatment with a single CDK4/6 inhibitor was ineffective in many GC patients." (PMID 36755269, 2023). "Our data show that targeting cancer-specific mutations in mitogenic signaling effectively reduced c-Myc and mRNA transcription rate, suppressing the development of CDK4/6i-tolerant persisters in cancer." (PMID 38030655, 2023). "CDK4 gene plays a significant role in the completion of the cell cycle and are often hyperactive in cancer." (PMID 37081847, 2023). "CDK4/6 inhibitors have radiosensitized cancer cells in preclinical studies by arresting cell cycle, reducing DNA damage repair, enhancing apoptosis, and causing cellular senescence." (PMID 37366898, 2023). "Our results present important clinical implications for the mechanism by which Cdk4/6 inhibitors induce permanent cell-cycle withdrawal in cancer cells." (PMID 37977116, 2023). "In a more recent study, LC-MS-based multi-omics analyses were used to investigate the mechanism of resistance to Palbociclib.This therapeutic drug is a specific CDK4/6 inhibitor that has been widely used in the therapy of various forms of cancer." (PMID 37893440, 2023). "Palbociclib, the first selective orally effective CDK4/6 inhibitor, has received approval for use in treating cancer." (PMID 37415164, 2023). "CDK4/6i effectively blocks the cell cycle proliferation from G1 (pre-DNA synthesis) to the S phase (DNA synthesis) by blocking the CDK4/6-cyclin D1 complex and preventing cancer cell proliferation and treatment resistance." (PMID 37567880, 2023). "Selective inhibitors of CDK4/6 are being tested in numerous clinical trials against various types of cancers." (PMID 37964967, 2023). "In cancer cells, Pxn phosphorylation is regulated by the kinase activity of Cdk4 and by the cytoplasmic Ccnd1, which colocalize with FA components, thus regulating cell invasion and metastasis." (PMID 37373242, 2023). "Formononetin showed inhibitory activity against cancer cells in vivo and in vitro, which is connected to G1 cell cycle arrest by the inactivation of Akt/cyclin D1/CDK4." (PMID 37298670, 2023).